TARDBP (TAR DNA binding protein)
Diseases named in the same sentence as TARDBP in open-access papers (continued):
Sharing a sentence is not in itself a finding about the gene and the disease.
Alzheimer disease (448 papers, 2008 to 2026). A progressive, neurodegenerative disease characterized by loss of function and death of nerve cells in several areas of the brain leading to loss of cognitive function such as memory and language. "For instance, APOE4 allele carriers exhibit accelerated amyloid-beta accumulation and reduced response to anti-Aβ therapies in Alzheimer’s disease, while TARDBP mutations drive TDP-43 proteinopathy in familial ALS, necessitating gene-targeted approaches." (PMID 40558545, 2025). "The ε4 allele of the APOE gene is a major genetic factor in Alzheimer's disease and has also been shown to increase the risk of TAR DNA-binding protein 43 (TDP-43) proteinopathy and hippocampal sclerosis in a large community-based cohort." (PMID 35115992, 2021). "It has been suggested that TDP-43 plays an important role in microglial phagocytosis, since microglial-specific knockout of TARDBP enhanced amyloid clearance and synaptic loss in an Alzheimer’s disease mouse model." (PMID 33427296, 2020). "PSP-CBS may cause difficulties in the differential diagnosis with Alzheimer’s disease (AD), frontotemporal lobar degeneration with TAR-DNA binding protein (FTLD-TDP), and corticobasal degeneration (CBD)." (PMID 35221993, 2022). "The most common protein inclusion in ALS is TDP-43 (encoded by the TARDBP gene); however, TDP-43 deposits have been observed in other neurodegenerative diseases such as Alzheimer’s disease (A.D.), Lewy bodies dementia (DLB), and corticobasal degeneration (CBD)." (PMID 33805659, 2021). "The cytoplasmic inclusion and mislocalization of TAR DNA-binding protein 43 (TDP-43) encoded by TARDBP is a pathological hallmark of more than 95% of ALS and a subset of FTD and Alzheimer’s disease cases." (PMID 38891021, 2024). "Such associations corroboratepatterns of neurodegeneration by specifically linking them with the underlyingcontributing pathology such as TAR DNA-binding protein 43 (TDP-43), phosphorylatedtau (p-tau), and α-synuclein in Alzheimer’s Disease (AD)." (PMID 39301426, 2024). "Mainly, limbic-predominant age-related TAR DNA-binding protein 43 encephalopathy (LATE) neuropathological changes are frequent during ageing and often associated with Alzheimer’s disease neuropathological changes." (PMID 35592489, 2022). "TDP-43 (TAR DNA-binding protein 43), another hnRNP, which, similar to FUS, is heavily implicated in the etiopathology of several neurodegenerative diseases including ALS and Alzheimer’s disease, also plays an important role in NHEJ-mediated DSB repair." (PMID 34026839, 2021). "In the presence of neurodegenerative disorders, such as pathologically confirmed Alzheimer’s disease (AD), other pathologies such as α-synuclein and TAR DNA-binding protein 43 (TDP-43) co-occur frequently." (PMID 34289895, 2021). "Microglia-specific knockout of TARDBP enhances amyloid clearance in an Alzheimer’s disease mouse model." (PMID 33427296, 2020). "In addition to α-synuclein pathology, previous studies frequently observed comorbid pathological conditions, including Alzheimer’s disease neuropathologic change, TAR DNA-binding protein 43 (TDP-43) pathology, and cerebral small vessel disease among others." (PMID 41185066, 2025). "Finally, many clinicopathological studies of dementia demonstrate that Alzheimer’s disease is frequently associated with other age-related processes, most commonly Lewy body disease (LBD) and TAR DNA-binding protein 43 (TDP-43) pathology." (PMID 37794477, 2023). "Disease-specific misfolded and aggregated proteins have been identified, such as amyloid-β and tau in Alzheimer’s disease, α-synuclein in Parkinson’s disease, huntingtin in Huntington’s disease, and superoxide dismutase 1 and TAR DNA-binding protein 43 (TDP-43) in ALS." (PMID 32403254, 2020).
Alzheimer disease (continued). "Accumulation of TAR DNA-binding protein 43 (TDP-43) containing cytoplasmic inclusions is a shared pathological hallmark in a broad spectrum of neurodegenerative disorders, including ALS, FTLD and Alzheimer's disease." (PMID 22957047, 2012). "TDP-43 pathology in the absence of TARDBP mutations is also found in hippocampal sclerosis of the elderly, as well as a subset of patients with Alzheimer’s disease, Parkinson’s disease or other neurodegenerative disorders, suggesting a pervasive involvement of TDP-43 in neurodegeneration." (PMID 22539017, 2012). "Adding to the complexity, other neurodegenerative disorders such as PSP, Alzheimer’s disease (AD), TAR DNA-binding protein of 43 kDa (TDP-43) proteinopathy, and dementia with Lewy bodies (DLB) can present with CBS indistinguishable from that observed in CBD." (PMID 39039147, 2024). "Pathological TAR DNA-binding protein (TDP-43) has been identified as a major component of insoluble aggregates in numerous neurodegenerative pathologies, including ALS, FTLD and Alzheimer’s disease." (PMID 36614118, 2022). "Here, we describe TAR DNA-binding protein 43 (TDP-43) proteinopathy and Alzheimer’s disease (AD) neuropathological changes in a beached harbor porpoise (Phocoena phocoena) that was exposed to a toxin produced by cyanobacteria called β-N-methylamino-L-alanine (BMAA)." (PMID 38251257, 2024). "However, USP12 does not generically suppress neurotoxicity, as overexpression of this enzyme in neuronal models of Parkinson’s and Alzheimer’s disease does not rescue the neuronal toxicity induced by TAR DNA-binding protein 43 (TDP-43) and α-synuclein." (PMID 38455765, 2024). "Inclusions of TAR DNA-binding protein 43 kDa (TDP-43) has been designated limbic-predominant, age-related TDP-43 encephalopathy (LATE), with or without co-occurrence of Alzheimer’s disease (AD)." (PMID 37605276, 2023).
dementia (206 papers, 2008 to 2026). Loss of intellectual abilities interfering with an individual's social and occupational functions. "Post-mortem neuropathological studies have indicated that with older age, other pathologies than AD also contribute to dementia risk such as TAR DNA-binding protein 43 (TDP-43) and hippocampal sclerosis." (PMID 31097030, 2019). "Limbic‐predominant age‐related TAR‐DNA‐binding protein‐43 (TDP‐43) encephalopathy with hippocampal sclerosis pathology (LATE‐NC + HS) is a neurodegenerative disorder characterized by severe hippocampal CA1 neuron loss and TDP‐43‐pathology, leading to cognitive dysfunction and dementia." (PMID 31376286, 2020). "Cognitive impairment and dementia in older adults often result from a combination of brain pathologies, including neurodegenerative changes such as Aβ plaques, tau NFTs, α-synuclein, TAR-DNA-binding protein 43 (TDP-43), and various cerebrovascular lesions." (PMID 41009474, 2025). "No additional variants were detected in PSEN2, APP, or other dementia causative genes (e.g., MAPT, GRN, and TARDBP)." (PMID 35932032, 2022). "Here, we evaluate BMAA exposure by investigating transcription signatures using PCR for dolphin genes homologous to those implicated in AD and related dementias: APP, PSEN1, PSEN2, MAPT, GRN, TARDBP, and C9orf72." (PMID 34678990, 2021). "No other pathogenic mutation in genes known to be associated with neurodegenerative diseases, and/or rare genetic causes of dementia, such as mutations in CHMP2B, FUS, TARDBP, SQSTM1 and VCP have been identified." (PMID 27632209, 2016). "Although it is unclear whether mtDNAcn in the blood is related to mtDNAcn in the brain, mtDNAcn from human blood and brain samples are both associated with dementia risk or brain pathologies of iron, tau, or TAR DNA-binding protein 43 (TDP-43)." (PMID 39313624, 2025). "Two families were negative for DIAD variants or other genes associated with autosomal dominant cause of dementia (e.g., MAPT, GRN, TARDBP, FUS), probands on those families were APOE4 carriers; 11 families are undergoing additional genetic counseling for future genetic testing." (PMID 35932032, 2022). "A pathology study showed that about two-thirds of patients with dementia show co-morbid molecular pathology in addition to plaques and tangles, namely α-synuclein aggregates, insoluble aggregates of TAR DNA-binding protein 43, and vascular pathology together with chronic inflammation." (PMID 36012569, 2022). "Neuroinflammation can induce and interact with many cellular and biochemical processes and consequently result in neuronal degeneration, phosphorylation of tau proteins, aggregation of TAR DNA-binding protein 43 (TDP-43), synaptic impairments, cognitive decline, and eventually dementia." (PMID 34831202, 2021). "Interestingly, variable clinical phenotype including dementia, atypical parkinsonism (CBD-like or PSP-like) and/or ALS is typical in Sardinian families with the TARDBP p.A382T founder mutation." (PMID 25853458, 2015). "However, when the analyses were controlled for other neuropathologies (NFT, NP, Tar-DNA binding Protein-43 and amyloid deposits), the associations between GVD and dementia lost significance." (PMID 26315613, 2015). "Older age is associated with an increase in dementia risk and cognitive decline attributable to the accumulation of multiple pathologies beyond those measured in this study, including neocortical Lewy bodies, TAR DNA-binding protein 43 (TDP-43) aggregations, and hippocampal sclerosis." (PMID 40682084, 2025). "The proteins most frequently involved in various forms of dementia are amyloid-β (Aβ), MAP Tau, α-synuclein (α-Syn), and TAR DNA-binding protein 43 (TDP-43)." (PMID 34769106, 2021). "Neurogranin (NRG), TAR DNA-binding protein 43 (TDP43), chitinase 3-like 1 (YKL40, cartilage glycoprotein-39), and kallikrein 6 (KLK6) are often found in classical AD and other dementias." (PMID 34944606, 2021).
dementia (continued). "‘Dementia’ observations were significantly lower in PSP cases than in other FTD subtypes, suggesting that this FTD subtype is less affected by dementia, whereas ‘compulsive behavior’ was consistently higher in FTD-TAR DNA-binding protein (TDP)-B, FTD-TDP-C compared with many other FTD subtypes." (PMID 38472295, 2024). "Moreover, the phenotypic heterogeneity of dementia reflects a broader spectrum of neurodegenerative conditions other than AD, including cerebrovascular infarctions, neocortical Lewy bodies, and TAR DNA-binding protein 43 (TDP-43), just to name a few." (PMID 23482655, 2013). "However, the large majority of brains with ADNC and documented dementia harbor one or more additional age-related pathologies at autopsy including but not limited to cerebrovascular disease, Lewy body inclusions, and TAR DNA-binding protein 43 (TDP-43) aggregates." (PMID 40501554, 2025).
Parkinson disease (206 papers, 2008 to 2026). A progressive degenerative disorder of the central nervous system characterized by loss of dopamine producing neurons in the substantia nigra and the presence of Lewy bodies in the substantia nigra and locus coeruleus. "More recently, the first TARDBP mutation outside exon 6 manifesting with parkinsonism was identified in a Chinese ALS family." (PMID 36247987, 2022). "Most ALS cases with TARDBP mutations manifesting parkinsonism were reported in the Italian population except for one Japanese pedigree." (PMID 36247987, 2022). "The phenotype of TARDBP mutations has also been expanded to include Parkinson’s disease and complex atypical parkinsonism." (PMID 25853458, 2015). "Environmental exposures to fine particulate matter (PM2.5) and ultrafine particle matter (UFPM) are associated with overlapping Alzheimer’s, Parkinson’s and TAR DNA-binding protein 43 (TDP-43) hallmark protein pathologies in young Metropolitan Mexico City (MMC) urbanites." (PMID 36287840, 2022). "A double mutation in KIF1A elicits brain deposition of MAPT/tau and TARDBP/TDP-43 (transactive response DNA-binding protein 43), accompanied by spasticity and parkinsonism." (PMID 41277110, 2026). "Their findings revealed a broader phenotypic spectrum of TARDBP mutations, including ALS, FTD, and Parkinson's disease." (PMID 40234983, 2025). "There are also several reports connecting TARDBP gene mutations, especially of A382T87, A315E, and N267S, with FTD and related parkinsonism." (PMID 40722695, 2025). "Mutations of TARDBP gene, mainly in exon 6 hotspot, have been reported to be causative of some forms of ALS and FTD, with clinical signs of parkinsonism observed in few mutation carriers." (PMID 36247987, 2022). "Forensic autopsies in children, teenagers and young adult residents in Metropolitan Mexico City (MMC) exhibited quadruple aberrant protein pathologies: Alzheimer’s disease (AD), Parkinson’s disease (PD) and TAR DNA-binding protein 43 abnormalities." (PMID 35448425, 2022). "For this reason, in this review we focus on parkinsonism in genetic forms of ALS–FTSD with confirmed TDP-43 proteinopathy, caused by mutations in C9orf72, PGRN, and TARDBP." (PMID 34943897, 2021). "Previously, mutations in SOD1, ANG, FUS/TLS, TARDBP and CHMP2B have been identified in patients with a range of clinical phenotypes, including combinations of FTD, Parkinson’s disease, and ALS." (PMID 23155438, 2012). "It seems that TARDBP mutations may have a broader symptomatic spectrum than other gene mutations in FTLD, as they may be associated with all three conditions: ALS, FTLD, and parkinsonism." (PMID 34943897, 2021). "Four other less common genetic links reported in familial FTD with parkinsonism cases are—chromatin modifying protein 2B (CHMP2B), transactive response DNA-binding protein (TARDBP), valosin-containing protein (VCP), and fused-in-sarcoma (FUS) genes." (PMID 33250855, 2020). "Since then, mutations in several other genes have been identified for FTLD with parkinsonism, including chromatin modifying protein 2B, chromosome 9 open reading frame 72 (C9ORF72), fused in sarcoma, valosin-containing protein, and transactive DNA-binding protein (TARDBP)." (PMID 29881367, 2018).
tauopathies (163 papers, 2009 to 2026). "While AD is characterized by the extraneuronal deposits of the amyloid β-protein (Aβ) and the intraneuronal tauopathy, ALS is primarily associated with TAR DNA-binding protein 43 (TDP-43) deposits." (PMID 30018591, 2018). "We will summarize recent advances in our understanding of the role of dysregulated IFN signaling in AD, primary tauopathy, TAR DNA-binding protein 43 (TDP-43) proteinopathy including cases associated with C9orf72 hexanucleotide repeat expansion (HRE), and Parkinson’s disease (PD)." (PMID 39421070, 2024). "FUS and TARDBP are FTLD genes, and DDX3X and TIA1 have been implicated in tauopathies." (PMID 37730840, 2023). "TAR DNA-binding protein 43 (TDP-43) pathology or fused in sarcoma (Fus) were more frequent than tauopathies, which may be seen in HD as well." (PMID 35222250, 2022). "In addition to unique patterning of tauopathies in CTE, subjects with TBI-induced CTE have increased expression of the TAR DNA-Binding Protein 43 (TDP-43), which is prominent in the neurites and intranuclear regions of neurons and glia." (PMID 30210334, 2018). "However, in both PCA and lvPPA a significant minority of cases showed other underlying pathologies than AD, e.g. Lewy bodies, transactive response DNA binding protein of about 43 kDa (TAR DNA-binding protein 43, TDP-43) proteinopathies, “pure” tauopathy or cerebrovascular disease." (PMID 31659510, 2019).
sarcoma (140 papers, 2009 to 2026). A usually aggressive malignant neoplasm of the soft tissue or bone. "Other mouse models of severe ALS with human TAR DNA-binding protein-43 or fused-in-sarcoma mutations also exhibit early NMJ pathology, similar to that observed in SOD1 mice." (PMID 40356623, 2025). "Repeat expansions in the C9ORF72 gene and mutations in superoxide dismutase 1 (SOD1) are common genetic causes of ALS, while TAR DNA-binding protein (TDP-43) and fused in sarcoma/translated in liposarcoma (FUS/TLS) mutations represent a smaller fraction." (PMID 38463392, 2024). "Most common are mutations in C9orf72 (chromosome 9 open reading frame 72), SOD1 (superoxide dismutase 1), FUS (fused in sarcoma), and TARDBP (encoding for TDP-43)." (PMID 35777956, 2022). "Intensive research over the last decade has proposed the ALS-causing gene products Cu/Zn superoxide dismutase 1, TAR DNA-binding protein of 43 kDa, and fused in sarcoma as very plausible prionoids contributing to the spread of the pathology." (PMID 35783556, 2022). "Some ALS-causing gene mutations encode RBPs, including transactive response DNA-binding protein 43 (TARDBP, which encodes TDP-43), fused in sarcoma/translocated in liposarcoma (FUS/TLS or FUS) and heterogeneous nuclear ribonucleoprotein A1 (hnRNPA1)." (PMID 34396115, 2021). "Among the pathological similarities between ALS and FTLD, one major hallmark is the accumulation of cytoplasmic inclusions of TAR DNA-binding protein 43 (TDP-43) or Fused in Sarcoma/Translocated in Sarcoma (FUS/TLS), which are both ubiquitously expressed in most cell types and tissues." (PMID 38111057, 2023). "Genes associated to inherited forms include those encoding the TAR DNA-binding protein 43 (TDP-43), the fused in sarcoma/translocated in liposarcoma RNA-binding protein (FUS/TLS), and an intronic GC repeat expansion in the chromosome 9 open reading frame 72 (C9ORF72)." (PMID 35453299, 2022). "Furthermore, TAR DNA-binding protein 43 (TDP-43) and fused in sarcoma protein, proteins associated with phase-separated compartments (e.g., stress granules) in cells, also have amyloid-forming domains." (PMID 34953857, 2022). "Mitochondrial dysfunction was evident in fibroblasts of ALS patients carrying pathogenic mutations in SOD1 (I113T), in FUS1 (fused in sarcoma; R521G), or in TDP43 (TAR DNA‐binding protein 43; G289S) genes and was associated with an increased Drp1 association with the mitochondria." (PMID 29335339, 2018). "We first determined whether mitochondrial dysfunction is evident in fibroblasts of ALS patients carrying pathogenic mutations in SOD1 (I113T), in FUS1 (fused in sarcoma; R521G) or in TDP43 (TAR DNA‐binding protein 43; G289S) genes." (PMID 29335339, 2018). "sTurbo TauRD shared 97 proteins with the TAR DNA-binding protein-43 interactome and 20 with the fused in sarcoma interactome, while more than 630 proteins were uniquely enriched in the TauRD interactome." (PMID 41205924, 2025). "The mutated genes involved are genes encoding Cu/Zn superoxide dismutase (SOD1), TAR-DNA binding protein 43 (TDP-43), fused in sarcoma/translocated in liposarcoma (FUS/TLS), and C9ORF72." (PMID 38524401, 2024). "Mutations in SOD1, TAR DNA-binding protein-43 (TDP-43), fused in sarcoma/translocated in liposarcoma (FUS/TLS, FUS), and open reading frame 72 on chromosome 9 (C9ORF72) genes are common in major cases of ALS." (PMID 38500677, 2024). "Aggregation of misfolded proteins due to mutation genes encoding SOD1 (superoxide dismutase 1), TDP-43 (TAR-DNA binding protein-43), and FUS/TLS (fused in sarcoma/translocated in liposarcoma) results in endoplasmic reticulum stress." (PMID 36788871, 2023). "This review will focus on two specific RNA-binding proteins implicated in ALS and FTD pathology: TAR DNA-binding protein 43 (TDP-43) and fused in sarcoma/translocated in liposarcoma (FUS/TLS)." (PMID 35187086, 2022).